ABCG2 (ATP binding cassette subfamily G member 2 (JR blood group))
Diseases named in the same sentence as ABCG2 in open-access papers (continued):
Sharing a sentence is not in itself a finding about the gene and the disease.
lung adenocarcinoma (12 papers, 2016 to 2025). A carcinoma that arises from the lung and is characterized by the presence of malignant glandular epithelial cells. "Our study demonstrated that ABCG2 was distributed not only in the ER-derived membranes (ER, Golgi apparatus, and plasma membrane), but also in the mitochondria of A549 (human lung adenocarcinoma cell line) and ST-HEK cells stably transfected with FLAG-ABCG2." (PMID 33670777, 2021). "Finally, we sorted ABCG2 cells derived from five patients with lung adenocarcinoma after permission." (PMID 29706625, 2018). "Targeting PLK1 with shRNA or non-functional mutants downregulated ABCB1, ABCC9, and ABCG2 in paclitaxel-resistant lung adenocarcinoma (LUADTXR), similar to the downregulation effects from treatment with PLK1 inhibitors." (PMID 34503223, 2021). "Noteworthy, for patients with lung adenocarcinoma a potential link between the ABCG2 expression and clinical outcome has been proposed; thus, expression of ABCG2 in combination with CD133 expression (ABCG2+/CD133+ NSCLC status) was found to be a predictor of a high risk of early relapse." (PMID 26967245, 2016).
lymphoma (12 papers, 2015 to 2024). A malignant (clonal) proliferation of B- lymphocytes or T- lymphocytes which involves the lymph nodes, bone marrow and/or extranodal sites. "However, the associations of the mutations of the ABCB1 or ABCG2 gene with drug resistance are unclear in human and canine lymphomas." (PMID 29061940, 2015). "Our previous studies also revealed that the JNK pathway downregulated ABCB1 gene expression and the MAPK/ERK and JNK pathways downregulated ABCG2 gene expression in those lymphoma cell lines." (PMID 29061940, 2015). "In addition, the coexpression of survivin and MRP1/ABCC1 indicates a potential drug-resistant mechanism through the activation of drug efflux pumps as ABC transporters (MRP1/ABCC1 as well as BRCP/ABCG2) and inhibition of lymphoma cell apoptosis." (PMID 37627134, 2023). "In contrast, some studies suggested that ABCG2 C421A polymorphism may be useful as a biomarker for the prediction of susceptibility to diffuse large B-cell lymphoma, lymphoma, and nonpapillary renal cell carcinoma." (PMID 29340035, 2017). "Cooperation between CD147 and the lymphatic vessel endothelial hyaluronan receptor-1 (LYVE-1) was also described in the regulation of chemoresistance in lymphoma through upregulation of the drug transporter/ABCG2 (BCRP, the breast cancer resistance protein)." (PMID 31744072, 2019). "It has generally been thought that lymphomas in humans and dogs acquire multidrug resistance from the continuous activation of drug transporters, such as ABCB1 and ABCG2, after long-term exposure to anticancer drugs, inducing chemical tolerance in the patient." (PMID 28489881, 2017).
thyroid cancer (12 papers, 2016 to 2025). "At the same time, our study also showed that overexpression of USP10 inhibited the malignant biological behavior of DOX-resistant thyroid cancer cells, while concomitant overexpression of ABCG2 reversed this inhibition caused by USP10." (PMID 37919637, 2023). "Our study also showed that overexpression of USP10 inhibited the malignant biological behavior of DOX-resistant thyroid cancer cells, while concomitant overexpression of ABCG2 reversed this inhibition caused by USP10." (PMID 37919637, 2023). "Mechanistically, overexpressing USP10 inhibits the invasion, migration and EMT of thyroid cancer cells by regulating the expression of ABCG2 and mediating PTEN/PI3K/AKT signaling pathway." (PMID 37919637, 2023). "At the same time, our study also showed that overexpression of USP10 inhibited the malignant biological behavior of DOX-resistant thyroid cancer cells by inhibiting the expression of ABCG2 by regulating the PTEN/PI3K/AKT pathway." (PMID 37919637, 2023). "ABCG2 expression has been reported to be more highly expressed in a number of thyroid cancer cell lines above that of their NSP and ABCB1 has been reported to be expressed in the N-thy ori-3-1 and BCPAP cell lines." (PMID 35118633, 2022). "A significant increase in Oct4 and ABCG2, a drug-resistant gene, is also associated with EMT induction in thyroid cancer." (PMID 34831219, 2021). "Importantly, the translocation of the ABCG2 drug transporter away from the plasma membrane resulted in a concomitant decrease in doxorubicin extrusion in thyroid cancer cell lines." (PMID 37919637, 2023). "Given that doxorubicin is also a substrate of ABCG2, the inhibition of ABCG2 and the resultant decreased efflux of doxorubicin likely underlie the observed synergism, similar to the interaction seen with the EGFR inhibitor gefitinib and doxorubicin in thyroid cancer." (PMID 39033209, 2024). "Expression levels of ALDH1A1, CD44, OCT3/4, and ABCG2 gene were 9.78, 7.02, 9.75, and 7.96 times more in stage III thyroid carcinoma than that in benign thyroid mass, respectively." (PMID 31341476, 2019). "To study the underlying mechanism by which USP10 could affect the biological characteristics of DOX-resistant FTC133-DOX thyroid cancer cells, we investigated PTEN/PI3K/AKT/ABCG2 signaling axis." (PMID 37919637, 2023). "However, it was previously reported that in thyroid cancer (mostly ATC), ABCG2 and ABCC1 proteins seem to be the most highly expressed transporters." (PMID 34073413, 2021). "Thyroid cancer stem cells have been identified and isolated from human thyroid glands based upon their higher aldehyde dehydrogenase (ALDH) activity, expression of ATP-binding cassette super-family G member 2 (ABCG2) and CD133." (PMID 31431834, 2019). "Furthermore, USP10 targeted ABCG2 to inhibit all these malignant processes, therefore, either increasing USP10 expression or inhibiting ABCG2 could be used as novel targets for treating DOX-resistant thyroid cancer." (PMID 37919637, 2023).
chronic kidney disease (11 papers, 2016 to 2025). Impairment of the renal function secondary to chronic kidney damage persisting for three or more months. "To clarify the physiological and pathophysiological roles of intestinal urate excretion via ABCG2 in humans, we genotyped ABCG2 dysfunctional common variants, Q126X (rs72552713) and Q141K (rs2231142), in end-stage renal disease (hemodialysis) and acute gastroenteritis patients, respectively." (PMID 27571712, 2016). "The impact of ABCG2 SNPs was even greater in chronic kidney disease patients who have lower renal urate excretion than in the general population." (PMID 36639673, 2023). "This study evaluated extra-renal urate excretion by ABCG2 in anuric patients with end-stage renal disease (hemodialysis patients) whose urate excretion depended on only the extra-renal pathway." (PMID 36639673, 2023). "In addition, if an end-stage renal disease patient develops acute gastroenteritis, both renal and intestinal urate excretion via ABCG2 will extremely decrease, and thereby greatly elevate SUA." (PMID 27571712, 2016). "OATs are important in maintaining residual tubular function in chronic kidney disease (CKD); as CKD progresses, intestinal transporters like ABCG2, which extrude urate and other organic anions into the gut lumen, seem to help restore homeostasis." (PMID 33937275, 2021). "Three well-characterized pathophysiological examples are the roles of OAT1, OAT3, URAT1, and ABCG2 in gout, the role of OAT1 and OAT3 in the accumulation of uremic toxins associated with chronic kidney disease (CKD), and the SLC22 family in acute kidney injury." (PMID 33757768, 2021). "Furthermore, in the setting of chronic kidney disease (CKD), intestinal extrusion of uric acid becomes relatively more important-presumably through inter-organ crosstalk with the injured kidney (resulting in increased expression and/or activity of ABCG2)." (PMID 36979028, 2023).
diffuse large B-cell lymphoma (11 papers, 2014 to 2023). "A study using diffuse large B cell lymphoma cells revealed that ABCG2 is a transcriptional target of the hedgehog signaling transcription factor GLI1." (PMID 31083682, 2019). "In this sense, it is evident that the Hh pathway promotes the expression of ABCG2 as GLI-1 is capable of binding to the promoter region of ABCG2, thus promoting resistance to therapy in diffuse large B-cell lymphoma." (PMID 28948003, 2017). "In addition, ABCG2 is a direct transcriptional target of the Hedgehog signaling pathway and is involved in drug tolerance in diffuse large B-cell lymphoma." (PMID 32688344, 2020).
oral cancer (11 papers, 2013 to 2023). "In addition, we found that oral cancer EpCAM+/ABCG2+ cells undergo inflammation and bacteria-mediated TS phenotype, which also contribute to rapid tumor progression." (PMID 36248858, 2022). "Furthermore, co-expressions of GBP5/CD166 (AHR = 2.48, CI = 1.08–5.74, p = 0.033) and GBP5/ ABCG2 (AHR = 2.65, CI = 1.25–5.61, p = 0.011) genes are associated with DFS in oral cancer patients from TCGA database." (PMID 34439200, 2021). "Therefore, using the natural compounds curcumin and EGCG to suppress ABCG2 expression in combination with PDT is a potential strategy to treat oral cancer." (PMID 32957726, 2020). "Elevated levels of ABCG2 is a marker to identify CSCs in oral cancer." (PMID 28704968, 2017). "Interestingly, ABCB5 marks a putative cancer stem cell compartment in oral cancer, and cancer stem cells of the laryngeal cancer cell line Hep-2 show an increase in ABCG2 expression." (PMID 23626764, 2013). "Also, ABCB1 and ABCG2 are expressed simultaneously in many cancer cells, including oral cancer." (PMID 28704968, 2017). "Third, REEP6 promotes drug resistance in TSCC cells, and oral cancer patients with an elevated co-expression of cancer stemness markers (CD166, ABCG2, ALDHA1) also had poor DFS." (PMID 37238941, 2023). "Subsequently, using a SCC-25 oral cancer–derived CSC model, we showed that hypoxia/reoxygenation or chemotherapy-induced TS enables ABCG2-positive sub-fraction of EpCAM+/ALDH1+/CD44v3+ CSCs to modulate TME for rapid tumor progression and immune suppression." (PMID 36248858, 2022). "HDAC inhibitors SAHA and TSA, also decreased cancer stem cell markers CD44 and ABCG2, and genes related with cellular stemness, as well as the EMT phenotype in oral carcinoma." (PMID 28704968, 2017). "On the other hand, it was demonstrated that the gene expression of Sox2 was upregulated in the Snail-overexpressing oral cancer cells, but the changes at the protein level were not significant (only Nanog, Bmi1, and ABCG2 were increased)." (PMID 35682836, 2022). "Moreover, a high co-expression of REEP6/CD166 (AHR = 2.28, 95%CI = 1.10–4.75, p = 0.027), REEP6/ABCG2 (AHR = 3.65, 95%CI = 1.42–9.41, p = 0.007) and REEP6/ALDH1A1 (AHR = 3.25, 95%CI = 1.34–7.90, p = 0.009) was related to the DFS of oral cancer patients in the TCGA database." (PMID 37238941, 2023).
ovarian tumor (11 papers, 2005 to 2025). "ABCG2 up regulation was shown to develop cisplatin and paclitaxel resistances in ovarian tumor cells." (PMID 40949794, 2025). "Activation of c-Kit has also been reported to increase WNT/β-catenin signaling and the expression of downstream targets of β-catenin, such as ABCG2, to regulate ovarian tumor-initiating capacity and chemoresistance." (PMID 32169072, 2020). "It has been found that c-Kit can mediate drug resistance and play an important role in regulating ovarian tumor-initiating cell survival and proliferation through the Wnt/β-catenin—ABCG2 pathway." (PMID 32169072, 2020). "It was also shown that ABCG2 level was increased in ovarian tumor-initiating cells (TIC/CIC/CSC) and depletion of either HIF-1α or ABCG2 reduced tumorsphere (cell aggregate) formation, demonstrating HIF-1α-to-ABCG2 axis in hypoxic tumorsphere." (PMID 30364132, 2018). "Increased levels of various transporters, such as ABCA1, ABCB5, and ABCC3/MRP3, have been demonstrated in ovarian tumour tissues, and an increased expression of ABCA1, ABCB1/MDR1/P-GP, and ABCG2/BCRP has been demonstrated in ovarian CSCs." (PMID 38201468, 2023). "Moreover, it has been reported that there were high levels of ABCA1, ABCB5, and ABCC3/MRP3 expressions in ovarian tumor tissues and high levels of ABCA1, ABCB1/MDR1/P-GP, and ABCG2/BCRP expression in ovarian CSCs." (PMID 31810474, 2019).
renal cell carcinoma (11 papers, 2013 to 2025). "ABCG2 mutations can also alter the survival progress in renal cell carcinoma patients." (PMID 36555598, 2022). "The polymorphisms of G34A and C421A in the ABCG2 gene have been reported to alter the expression or activity of ABCG2 and predispose carriers to a high risk of developing cancers such as nonpapillary renal cell carcinoma, DLBCL, and hormone-refractory prostate cancer." (PMID 26634205, 2015). "Several studies have reported a role of ABCG2 in the progression or prognosis of renal cell carcinoma." (PMID 36555598, 2022). "This study aimed to evaluate the associations of ABCG2 and ABCB1 polymorphisms with sunitinib-induced toxicity and efficacy in renal cell carcinoma (RCC) by meta-analysis." (PMID 33762959, 2021). "This is the first report on the sequence analysis of the substrate binding pocket ABCG2 from tumor tissue of renal cell carcinoma." (PMID 23467750, 2013). "Interestingly, we found that ABCG2 expression significantly correlated with Fuhrman grade in renal cell carcinoma." (PMID 28347288, 2017). "In renal cell carcinoma (RCC) and colon cancer cell lines exhibiting MDR and augmented ABCB1 expression, we have identified PITX2 as a contributor to chemotherapeutic drug resistance through transcriptional upregulation of ABCB1 as well as ABCC1, ABCG2, and the drug uptake transporter, SLC22A3." (PMID 35582031, 2021).
metabolic syndrome (10 papers, 2014 to 2024). A cluster of metabolic risk factors for CARDIOVASCULAR DISEASES and TYPE 2 DIABETES MELLITUS. "At first, ABCG2 is critical in removing excess cholesterol; the loss of function variant in the ABCG2 gene (rs2231142) leads to the inhibition of ABCG2 function, thus resulting in dyslipidemia." (PMID 38589776, 2024). "ABCG2 234AA genotype exposed an insignificant risk for development of dyslipidemia (P = 0.44, OR = 3.24) when compared between impaired cholesterol level and normal cholesterol level among patients without HIVLD." (PMID 37324630, 2023). "This is the first study which independently evaluates the influence of the MTP -493G/T and ABCG2 34G/A polymorphisms and its haplotype with respect to the risk of dyslipidemia and severity of LDHIV from Western India." (PMID 37324630, 2023). "Polymorphisms of the ABCG2 gene, biochemical parameters, and metabolic syndrome markers in this cohort were previously investigated in one of our other studies." (PMID 32759716, 2020). "Since the expression levels of ABCG2 are primarily determined by rs2231142, it indicates that the rs2231142 variant may induce dyslipidemia by modulating ABCB1 expression." (PMID 38589776, 2024). "Since the expression levels and function of ABCG2 are primarily determined by the rs2231142 variant, it is tempting to speculate that the rs2231142 variant may result in dyslipidemia." (PMID 38589776, 2024). "ABCG2 34GA genotype was likely to be associated with impaired triglyceride level with marginal significance and have been shown an increased risk for dyslipidemia (P = 0.07, OR = 2.76) when compared between impaired triglyceride level and normal triglyceride level among patients without HIVLD." (PMID 37324630, 2023). "This change cannot be explained based on the genetics of ABCG2 or by common features of metabolic syndrome, such as BMI." (PMID 38042879, 2023). "Individuals who have impaired LDL, HDL, triglyceride, and cholesterol levels with MTP -493GT and MTP -493TT and ABCG2 234AA genotypes showed a trend of the risk for severity of LDHIV and dyslipidemia, respectively." (PMID 37324630, 2023). "Identified variants were evaluated in relation to clinical data, biochemical parameters, metabolic syndrome criteria, and our previous analysis of the major secretory urate transporter ABCG2." (PMID 32759716, 2020). "This suggests that patients with and without HIVLD who have impaired cholesterol level and MTP -493GT and MTP -493TT and ABCG2 34AA genotypes may have a risk for severity of LDHIV and dyslipidemia, respectively." (PMID 37324630, 2023). "In patients without HIVLD, the ABCG2 34GA genotype was associated with impaired triglyceride levels with marginal significance and showed an increased risk for the development of dyslipidemia (P = 0.07, OR = 2.76)." (PMID 37324630, 2023). "ABCG2 34AA genotype displayed a non-significant risk for development of dyslipidemia (P = 0.46, OR = 1.94)." (PMID 37324630, 2023). "This suggests that patients with and without HIVLD who have impaired HDL level and MTP -493GT and MTP -493TT and ABCG2 34GA genotypes may have a risk for severity of LDHIV and dyslipidemia, respectively." (PMID 37324630, 2023).
nasopharyngeal carcinoma (10 papers, 2012 to 2020). A carcinoma arising from the nasopharyngeal epithelium. "ABCG2, an ABC transporter member, is associated with the formation of side population and stem/progenitor features in nasopharyngeal carcinoma." (PMID 25099028, 2014). "Interestingly, for Asian nasopharyngeal carcinoma patients, polymorphisms in the ABCG2 and ABCB1 genes could be predictive markers of drug (irinotecan) activity." (PMID 25965825, 2015). "Our previous study found that ABCG2+ subset existed in nasopharyngeal carcinoma cells with cancer stemness phenotype." (PMID 32168902, 2020). "Similar to our results, it has been reported that IRF6 directly binds the promoter of ABCG2, reduces its transcription, and decreases ABCG2 expression, thereby inhibiting proliferation and reversing the phenotype of nasopharyngeal carcinoma stem cells." (PMID 32527996, 2020). "In nasopharyngeal carcinoma cells (NPC), stem cell markers Oct4 and ABCG2 diminish when Drp1 activation (p-Drp1 Ser 616) is downregulated by Cox2 blockade, indicating the loss of stemness." (PMID 31089338, 2019). "A recent study has shown that spheres derived from nasopharyngeal carcinoma (NPC) cells possess CSC properties, express stemness proteins (Oct-4 and Nanog) and drug-resistant genes (MDR-1 and ABCG2), and undergo the EMT through increased CD44 expression." (PMID 26064420, 2015).